RN7SL638P (RNA, 7SL, cytoplasmic 638, pseudogene)
Gene: Miscellaneous RNA gene on chromosome 20 (18,592,330 to 18,592,619, forward strand). Ensembl gene ENSG00000243702.
Homologues: Orthologues: chimpanzee Metazoa_SRP (98% identical), macaque Metazoa_SRP (87% identical). Paralogues in human: RN7SL1 (80% identical), RN7SL3 (80% identical), RN7SL2 (79% identical), RN7SL709P (79% identical), RN7SL600P (78% identical), RN7SL473P (78% identical), RN7SL220P (77% identical), RN7SL448P (77% identical), RN7SL660P (77% identical), RN7SL664P (77% identical), RN7SL786P (77% identical), RN7SL321P (77% identical), and 700 more.